MUTYH (mutY DNA glycosylase)
Diseases named in the same sentence as MUTYH in open-access papers (continued):
Sharing a sentence is not in itself a finding about the gene and the disease.
colorectal cancer (continued). "However, even though more than 80 MUTYH variants have been described in the MUTYH gene in colorectal polyposis and colorectal cancer patients, the effect of only a small number of variations on human MUTYH protein activity has been investigated." (PMID 20848659, 2010). "Similarly, all individuals with a single, heterozygous P/LP variant in MUTYH have an estimated twofold increased risk of colorectal cancer, and current guidelines indicate that carriers who have a first-degree relative with colorectal cancer should consider more frequent colonoscopy screenings." (PMID 34404389, 2021). "In 2002, two autosomal recessive inherited mutations in MUTYH, Y165C and G382D, were associated with adenomatous polyposis and colorectal cancer, and several additional studies have confirmed that bi-allelic mutation carriers have an increased risk of developing colorectal cancer." (PMID 19338676, 2009). "Biallelic germline mutations in the MUTYH gene predispose patients to MUTYH-associated polyposis (MAP), which is associated with a lifetime risk of colorectal cancer, typically associated with colonic polyps." (PMID 40823072, 2025). "The MUTYH gene is involved in DNA repair and is known for MAP (MUTYH‐associated polyposis), an autosomal recessive disorder that predisposes individuals to colorectal cancer (CRC), with a lifetime risk ranging from 40% to 90%." (PMID 41001951, 2025). "Defects in one such gene, MUTYH, are known to elevate the incidence of colorectal cancer in a recessive Mendelian manner." (PMID 39403956, 2024). "Biallelic mutations of the MUTYH gene are implicated in MAP, and carriers of this mutation have an increased lifetime risk of developing colorectal cancer of 43% to 100%, depending on the appropriate screening and surveillance steps taken." (PMID 38586659, 2024). "Mutations of the MUTYH gene have been most frequently associated with MUTYH-associated polyposis (MAP) and colorectal cancer." (PMID 38586659, 2024). "In the present study we focused on the roles of base excision repair glycosylases (hOGG1, MUTYH) in colorectal cancer patients by investigating tumor and adjacent mucosa tissues." (PMID 35628513, 2022). "MUTYH mutations are the cause of MUTYH-associated polyposis (MAP), a syndrome that predisposes to colorectal polyposis and colorectal cancer." (PMID 33827469, 2021). "Much of the existing literature on MUTYH function comes from colorectal cancer; however, this data provides foundational information that is critical for understanding its role in ovarian cancer." (PMID 33419231, 2021). "The roles of base excision repair glycosylases (hOGG1, MUTYH) in tumor and adjacent mucosa tissues of colorectal cancer patients, particularly in the interplay with other factors (especially microenvironment), deserve further attention." (PMID 32252452, 2020). "The patient harboring a pathogenic variant in MUTYH (p.Gly396Asp, PRI-117 III-1) was diagnosed with breast cancer at the age of 50 and had a brother with early onset colorectal cancer." (PMID 31780696, 2019). "Biallelic mutations in MUTYH are associated with MUTYH-Associated polyposis (MAP) and increased risk in colorectal cancer (CRC)." (PMID 26109431, 2015). "A Brazilian female patient (FAP15) from the Hereditary Colorectal Cancer Registry of Hospital AC Camargo (São Paulo, Brazil), who was clinically suspected for MAP, was screened for mutations in the MUTYH gene by direct sequencing." (PMID 21962078, 2011).
colorectal cancer (continued). "Our findings suggest that the MUTYH Gln324His and the APEX1 Asp148Glu constitutes an increased risk of colorectal cancer, especially colon cancer." (PMID 18823566, 2008). "Although inherited susceptibility is responsible for ∼30% of all colorectal cancers (CRCs), high-penetrance, germline mutations in APC, the mismatch repair (MMR) genes, MUTYH/MYH, SMAD4, ALK3 and STK11/LKB1 account for <5% of cases." (PMID 18362937, 2008). "MUTYH encodes a base excision repair protein that interacts with the MMR system, and MUTYH variants have been associated with an increased susceptibility of colorectal cancer in a recessive manner." (PMID 39440754, 2025). "A third expression pattern is seen in the colorectal carcinoma or adenoma of patients carrying biallelic MUTYH variants: nuclear expression is absent, whereas cytoplasmatic expression is strong both in the neoplastic and surrounding healthy mucosa." (PMID 38790183, 2024). "In nonsporadic colorectal cancer, defective MUTYH results in a relatively modest mutator phenotype; nevertheless, it is an important risk factor for colorectal cancer." (PMID 37568604, 2023). "The biallelic variation in MUTYH causes the development of MUTYH-associated polyposis (MAP) and colorectal cancer; the monoallelic variation in MUTYH primes the carriers to develop colorectal cancer, although the risk is lower than for the biallelic germline variation." (PMID 36979362, 2023). "Thus, currently targeted therapy regarding ERCC1 has evolved for MUTYH, which is a glycosylase involved in the BER pathway and associated with colorectal cancer, and for MTHFR, interacting with folate synthesis and being prognostic in various cancers." (PMID 36497451, 2022). "A small proportion of colorectal cancers, which are not included in our analysis, are directly caused by inherited gene mutations, including mutations of the MUTYH gene or mismatch repair genes." (PMID 34071236, 2021). "We describe a family severely affected by colorectal cancer (CRC) where whole‐exome sequencing identified the coinheritance of the germline variants encoding MSH6 p.Thr1100Met and MUTYH p.Tyr179Cys in, at least, three CRC patients diagnosed before 60 years of age." (PMID 32615015, 2020). "An additional six individuals were also found to have pathogenic heterozygous mutations in MUTYH in the absence of a personal or family history of colorectal cancer or polyposis." (PMID 30875412, 2019). "The present retrospective cohort study aimed at investigating whether MLH1,APEX1,MUTYH,OGG1,NUDT1,XRCC5, XPA, and ERCC2 single nucleotide polymorphisms (SNPs) are associated with colorectal cancer (CRC) in Chinese population with Lynch syndrome." (PMID 29664240, 2018). "Of the two individuals who carried two DV in genes other than MUTYH, one was affected with colorectal cancer and carried a DV in CHEK2 and PALB2, while the second was not personally affected with cancer but did have a family history of breast and gastric cancer and carried DV in PMS2 and CDH1 genes." (PMID 29308099, 2018). "The genes mostly implicated in the inheritance of adenomatous polyposis, a condition that leads to colorectal cancer, are adenomatous polyposis coli (APC) involved in FAP (OMIM #175100) and mutY Homolog (MUTYH) involved in MUTYH-associated polyposis (MAP) (OMIM#608456)." (PMID 26511139, 2015). "Some population based studies showed that ~30% of biallelic MUTYH mutation carriers develop a colorectal cancer in the absence of a polyposis phenotype." (PMID 26557847, 2015).
colorectal cancer (continued). "Regarding genetic counseling, we found 4 monoallelic MUTYH mutation carriers that were notified of their status, based on NCCN guidelines, which suggest increased screening only for monoallelic carriers with a personal or first-degree family history of colorectal cancer or polyps." (PMID 40823072, 2025). "Interestingly, our study does not detect a relationship between MUTYH mutations and colorectal cancer." (PMID 38254803, 2024). "It is not known whether mutations or polymorphisms in MUTYH are specific for colorectal cancer or if they encompass a larger spectrum of disease, especially that which is over-represented in Lynch Syndrome." (PMID 19338676, 2009). "Thus, for colorectal cancer, it is also possible that the enzyme of MUTYH Gln324His may have partially impaired in repair of 2-OH-A opposite guanine, compared to repair of adenine opposite 8-oxo-G, because of the difference in the origin of each oxidized base." (PMID 18823566, 2008). "Bi-allelic carriers (with mutations in both alleles of the MUTYH gene, i.e. a MAP patient) develop polyposis and subsequently colorectal carcinoma (CRC) in the majority of cases." (PMID 17605803, 2007). "MUTYH and OGG1 tissue expression was quantified by RT-PCR in patients with colorectal cancer and the values were compared in normal and neoplastic tissues." (PMID 29257843, 2017). "Since early-onset colorectal cancer (CRC) is a characteristic of MAP and might be caused by the inactivation of another 8-hydroxyguanine repair gene, OGG1, we investigated whether germline MUTYH and OGG1 mutations are involved in early-onset CRC in Japanese patients." (PMID 24799981, 2014). "Germline biallelic pathogenic MUTYH variants predispose patients to colorectal cancer (CRC); however, approaches to identify MUTYH variant carriers are lacking." (PMID 35668106, 2022). "Oka and colleagues (2014) demonstrated that MUTYH knockdown colorectal cancer cells exposed to oxidative stress failed to undergo PARP-mediated apoptosis, resulting in aberrant cell growth and risk for tumorigenesis." (PMID 33419231, 2021). "Although no studies have investigated the effect of mutant MUTYH in ovarian cancer cells, the mechanism for ovarian cancer oncogenesis is likely similar to that of colorectal cancer carcinogenesis as both of these cancers are established in the MAP phenotype." (PMID 33419231, 2021). "The MUTYH and OGG1 genes present downregulation in the more advanced stages of colorectal cancer." (PMID 29257843, 2017). "In particular, recent published works point out at other genes implied in colorectal cancer pathogenesis (APC, MUTYH, STK11 and BRCA1/2) as explanations of familial colorectal cancer syndromes in patients who do not present mutations in standard MMR protein gene system." (PMID 26485756, 2015).
polyposis (100 papers, 2007 to 2026). "(iii) MUTYH-Associated Polyposis (MAP): MAP results from biallelic mutations in the MUTYH gene, leading to a high lifetime risk of CRC, though generally lower than that seen in FAP." (PMID 41541272, 2025). "The GPP rate was especially high for the MUTYH and ATP7B genes, which indicate a high carrier rate of MUTYH-Associated Polyposis and Wilson disease in the Qatari population." (PMID 39020067, 2024). "Underperformance of the mammalian homolog, MUTYH, leads to early onset cancer in humans, first discovered for a class of colon cancers now recognized as MUTYH Associated Polyposis." (PMID 38718041, 2024). "MUTYH was identified as the first gene to cause an autosomal recessive inherited form of polyposis, named MUTYH-associated polyposis (MAP)." (PMID 38467732, 2024). "In contrast, MUTYH is primarily associated with MUTYH-associated polyposis, exhibiting some phenotypic similarities to Lynch syndrome." (PMID 38136308, 2023). "The polyps in the four subjects in the present study were primarily located in the proximal colon (75%), as also seen in attenuated familial adenomatous polyposis and MUTYH-associated polyposis." (PMID 35675019, 2023). "From these, one Familial Adenomatous Polyposis and one MUTYH-associated Polyposis were diagnosed (both in patients with multiple adenomas)." (PMID 35954394, 2022). "Lynch syndrome was predominant (n = 73) followed by familial adenomatous polyposis (n = 12) and MUTYH‐associated polyposis (n = 8); the latter of which two patients presented with CRC before polyposis was evident." (PMID 35430768, 2022). "In particular, the MUTYH p.(Gly368Asp) and p.(Tyr151Cys) variants are well-established pathogenic variants for MUTYH-related polyposis and are estimated to account for 50–82% of MUTYH-associated polyposis in European patients." (PMID 36035419, 2022). "MUTYH is involved in base excision repair and biallelic germline mutations in it cause MUTYH-associated polyposis." (PMID 35739278, 2022). "Sporadic panNETs arose in 141 patients with panNET-associated familial syndromes in 42 individuals: 36 with MEN1, 2 with VHL, 1 each with TSC, NF1, paraganglioma, MAX mutation and MUTYH-associated polyposis." (PMID 34163434, 2021). "The variable phenotype of MUTYH-associated polyposis can overlap the LS phenotype, and biallelic MUTYH germline variants impairing the base-excision repair (BER) pathway can sometimes lead to biallelic somatic variants in MMR genes and to MSI/dMMR tumors." (PMID 33530449, 2021). "This suggest that only if both MUTYH alleles are affected, this results in signature 36, similar to the biallelic variants in patients with MUTYH-associated polyposis." (PMID 34479993, 2021). "These genes are known to be involved in MUTYH Associated Polyposis and in Wilson disease, respectively." (PMID 32231684, 2020). "MUTYH-associated polyposis is extremely variable, ranging from severe polyposis coli to attenuated forms with a late age of onset or few adenomas, or CRC, which creates a phenotypic overlap with LS." (PMID 32973888, 2020). "Although few studies have been conducted on the study of MUTYH variants in Asian polyposis patients." (PMID 31724937, 2019). "In the Western countries, MUTYH is the second leading cause of APC variants in patients with polyposis." (PMID 31724937, 2019). "In the genetics analysis two mutations were observed in the MUTYH gene, and MUTYH-associated polyposis was diagnosticated." (PMID 30953464, 2019). "The mutation observed in MUTYH is known to be pathogenic and involved in MUTYH-associated polyposis, an autosomal recessive disorder." (PMID 30233642, 2018). "Current ACMG guidelines for the reporting of incidental findings recommend only reporting compound heterozygous or homozygous variants in MUTYH, as MUTYH-associated polyposis is considered a recessive disease." (PMID 30487145, 2018).
polyposis (continued). "MUTYH-associated polyposis is caused by biallelic mutations in the MUTYH gene and tends to have a similar number of polyps as patients who have AFAP." (PMID 28283772, 2017). "The c.1187G>A (p.Gly396Asp) variant is a common cause of MUTYH-associated polyposis in individuals of Northern European ancestry and experimental studies have shown that this missense variant disrupts MUTYH protein function." (PMID 27014339, 2016). "Germline mutations of POLD and POLE were shown to predispose individuals to a polyposis-phenotype with large adenomas similar to that observed in MUTYH-associated polyposis or early onset and multilocated cancers, respectively." (PMID 25124163, 2014). "This first comprehensive investigation of the APC and MUTYH mutation spectrum in Brazilian polyposis patients showed a high detection rate and identified novel pathogenic mutations." (PMID 23561487, 2013). "Considering that this study is the first comprehensive analysis of APC and MUTYH mutations in Brazilian polyposis patients, we attempted to determine the most cost-effective approach to detect the causative mutation in this population." (PMID 23561487, 2013). "In 2002, Al-Tassan and coworkers described for the first time a recessive form of polyposis associated with biallelic mutations of MUTYH; this gene encodes a base excision repair (BER) protein that counteracts DNA damage induced by oxidative stress." (PMID 22876359, 2012). "Biallelic MUTYH germline mutations were found in 8.5%, i.e. 7/82 which also showed an attenuated polyposis phenotype." (PMID 20687945, 2010). "Defects in the base excision repair gene MUTYH are responsible for MUTYH-associated polyposis and CRC predisposition as an autosomal recessive trait." (PMID 21063410, 2010). "In this study, we examined the mutational spectrum of the APC gene in patients with polyposis from two Spanish populations, and also the contribution of MUTYH germline mutations in those APC-negative patients." (PMID 19531215, 2009). "Biallelic germline mutations in MUTYH accounted for 24% of the families analysed, all of which displayed an attenuated polyposis phenotype and a CRC onset 10 years later than FAP." (PMID 19531215, 2009). "Since the discovery of the MUTYH gene in 2002, hundreds of patients have been diagnosed with MUTYH-associated polyposis." (PMID 17605803, 2007). "In cases of genetic predisposition observed in familial adenomatous polyposis (FAP), hereditary nonpolyposis colorectal cancer (HNPCC), and mutY DNA glycosylase (MUTYH)-associated polyposis, they are often identified earlier because of heightened screening recommendations." (PMID 40429526, 2025). "However, pathogenicity in MUTYH is typically associated with bi-allelic variants, particularly in the context of MUTYH-associated polyposis." (PMID 40995433, 2025). "Moreover, we found no discernible SBS88 signature that is linked to colibactin and was reported to occur in colorectal tumors from NTHL1- and MUTYH-associated polyposis patients." (PMID 38725616, 2024). "Additionally, a heterozygous monoallelic MUTYH (NM_001128425.2) variant c.1187G>A (p.Gly396Asp) was detected, which is associated with MUTYH-associated polyposis only in bi-allelic (homozygous/compound heterozygous)." (PMID 37685569, 2023). "Besides, 12 subjects carried at least one high-risk recessive allele (12/27, 44.4%) either in ATP7B or in MUTYH gene, causative of Wilson disease and MUTYH-associated polyposis, respectively." (PMID 36437915, 2022).